GIMAP5 (GTPase, IMAP family member 5)
Description:
Plays a role in T lymphocyte development and the optimal generation of CD4/CD8 double-positive thymocytes (By similarity). Inhibitor of GSK3A, possibly by sequestering GSK3A in cytoplasmic vesicles and impairing its translocation to the nucleus. Consequently, impairs GSK3A-dependent transcriptional program and regulation of the DNA damage response occurring during T cells proliferation. Required for the survival of peripheral T cells, natural killer (NK) and NK T-cell development and the maintenance of normal liver function (By similarity). May promote the survival of mature T lymphocytes upon cytokine withdrawal (By similarity). May regulate Ca(2+) homeostasis by modulating lysosomal Ca(2+) stores, preventing its accumulation in the absence of T cell activation (By similarity). May play a role in mitochondrial DNA segregation in hematopoietic tissues (By similarity). Is a regulator of liver endothelial cell homeostasis (By similarity).
Synonyms: IAN-5; IAN4L1; IAN5; IMAP3; HIMAP3; IAN4; IROD; NCPH2
Tractability: Small molecule: a structure with a bound ligand is known. Antibody: UniProt places it where antibodies can reach, with medium confidence; UniProt predicts a signal peptide or a membrane-spanning region. PROTAC: ubiquitination databases record sites on it; its protein half-life has been measured.
Gene: Protein-coding gene on chromosome 7 (150,722,253 to 150,750,033, forward strand). Ensembl gene ENSG00000196329.
Subcellular location: Lysosome membrane; Endosome, multivesicular body membrane; Endosome membrane
Gene Ontology:
Molecular function: protein binding; GTPase activity; GTP binding
Cellular component: lysosomal membrane; endosome membrane; multivesicular body membrane
Genetic constraint (gnomAD): Loss-of-function variants: 9 observed, 11.34 expected, observed/expected ratio (o/e) 0.79, 90% interval 0.48 to 1.38. The upper end of that interval is the gene's LOEUF score, 1.38, which puts it in group 5 of 6, group 1 being the genes least tolerant of losing a copy. Missense variants: 353 observed, 384.37 expected, observed/expected ratio (o/e) 0.92, 90% interval 0.84 to 1. Synonymous variants: 174 observed, 157.98 expected, observed/expected ratio (o/e) 1.1, 90% interval 0.97 to 1.25.
Homologues: Orthologues: chimpanzee GIMAP1 (98% identical), macaque GIMAP5 (77% identical), dog GIMAP5 (66% identical), guinea pig GIMAP5 (59% identical), mouse Gimap5 (55% identical), mouse Gimap3 (54% identical), rat Gimap5 (51% identical). Paralogues in human: GIMAP1 (37% identical), GIMAP2 (37% identical), GIMAP6 (34% identical), GIMAP7 (33% identical), GIMAP4 (32% identical), GIMAP8 (30% identical), GIMD1 (18% identical).
Diseases named in the same sentence as GIMAP5 in open-access papers:
GIMAP5 is named in the same sentence as 29 diseases in open-access papers, as found by Europe PMC text mining. Sharing a sentence is not in itself a finding about the gene and the disease. The quoted sentences say what the papers report.
lymphopenia (20 papers, 2009 to 2025). Reduction in the number of lymphocytes. "First, the introgression of a 33-Mb region of the F344 genome, proximal to the mutated Gimap5 gene, renders the rat diabetes resistant despite having lymphopenia." (PMID 41042382, 2025). "Previous work on Gimap5 knockout mice and the spontaneous rat lymphopenia (lyp) mutation in Gimap5 has indicated that the residual T lymphocyte populations are atypical compared to wild type." (PMID 29718959, 2018). "This possibility has been strengthened by genetic and cellular studies of the lymphopenias and cell death associated with GIMAP5 and GIMAP1 deficiencies which cast doubt on the involvement of the BCL2-related apoptotic machinery in the lymphopenias." (PMID 29718959, 2018). "Loss of function GIMAP5 mutation is associated with lymphopenia, but how it mediates T cell homeostasis is unclear." (PMID 29382851, 2018). "The patient presents with an immunodeficiency strikingly similar to Gimap5-deficient mice, including the development of lymphopenia, reduction in TFs such as c-Myc, as well as increased DNA damage and reduced survival upon T cell activation." (PMID 29382851, 2018). "In mice and in rats, the loss of functional GTPase of the immune associated nucleotide binding protein 5 (GIMAP5) causes peripheral T lymphopenia due to spontaneous death of T cells." (PMID 26440416, 2015). "Genetic aberrations in Gimap5 have been linked to lymphopenia and the loss of immunological tolerance." (PMID 25038616, 2014). "A spontaneous mutation of GIMAP5 in rats, as well as both a mutation and a targeted deletion of GIMAP5 in mice, produce severe peripheral lymphopenia in the T lymphocyte lineage." (PMID 24204963, 2013). "These animals show a mutation in the Gimap5 gene, which not only results in lymphopenia, but also in decreased numbers of regulatory T cells." (PMID 23805184, 2013). "Genetic deficiencies in either GIMAP5 or GIMAP1 produce severe peripheral lymphopenias in rodent models." (PMID 24204963, 2013). "Our data substantiates the Gimap5 frameshift mutation as the primary defect with only limited contributions to lymphopenia from the remaining Gimap genes." (PMID 19421422, 2009). "Positional cloning of lymphopenia (lyp) in the BB rat revealed a frameshift mutation in Gimap5, a member of at least seven related GTPase Immune Associated Protein genes located on rat chromosome 4q24." (PMID 19421422, 2009). "Therefore, while the Gimap5-DP rats show a clear T cell deficiency indicative of lymphopenia, further studies are needed to confirm total lymphocyte counts below the clinical threshold (< 1,500 cells/μL)." (PMID 41042382, 2025). "Finally, we show that a human patient with a GIMAP5 loss-of-function mutation has lymphopenia and impaired T cell proliferation in vitro that can be rescued with GSK3 inhibitors." (PMID 29382851, 2018). "In addition to NOD mice, it has been shown that a mutation in Gimap5 gene results in lymphopenia and is a prerequisite for spontaneous IDDM in the BioBreeding (BB) rat." (PMID 24586733, 2014). "However, the amino acid differences do notappear to have functional effects substantiating the Gimap5 frameshift mutation as the cause of lymphopenia." (PMID 19421422, 2009). "While the frameshift mutation in Gimap5 is likely necessary andsufficient for lymphopenia, the possibility remains that additional mutation(s)in the Gimap family may contribute tothe development of lymphopenia, spontaneous T1D, or both in the DR.lyp/lyp rat." (PMID 19421422, 2009). "However, the peripheral T lymphopenia in the Gimap5lyp/lyp rats suggests that the homeostatic expansion may also be compromised by GIMAP5 deficiency or, alternately, that the expanding cells are unable to survive and persist in the secondary lymphoid organs." (PMID 34135906, 2021). "Therefore, the sequence analysis of Gimap1 and Gimap3 supports the hypothesis that Gimap5 is the cause of lymphopenia in the DR.lyp/lyp rat." (PMID 19421422, 2009).
lymphopenia (continued). "In contrast, the Gimap5−/− (Gimap5-DP) rats–characterized by lymphopenia –displayed a distinct spike in CD3+ T cell density at the islet periphery, with little infiltration into the islet core." (PMID 41042382, 2025). "Gimap5 deficiency can result in the constitutive activation of AKT/mTORC1 pathway, which causes peripheral T lymphopenia." (PMID 31579581, 2019). "In BBDP rat, 215 amino acids in Gimap5 C-terminal were replaced by 19 other amino acids where transmembrane domain was truncated which leaded to lymphopenia (Hornum, Romer & Markholst, 2002)." (PMID 31579581, 2019). "Dissecting the relative contribution of lymphopenia to the signaling pathways in naïve T cells where GIMAP5 appears to be required for both TCR and IL-7 mediate signaling, will be a challenge." (PMID 27023180, 2016). "Despite the lymphopenia and the defective proliferative response following TCR stimulation, Gimap5-deficient T cells do differentiate into Th17 cells and contribute to tissue pathologies." (PMID 26440416, 2015). "An extensively studied genetic defect of lymphopenia (i.e., lyp, also called Iddm2) in diabetes-prone BioBreeding rat (BBDP) was shown to be caused by a frameshift mutation in the Gimap5 gene." (PMID 21637352, 2010). "Lymphopenia in the BBDP rat was originally linked to a recessive mutation in a diabetes susceptibility locus designated lyp/Iddm1, which encodes for Gimap5 protein." (PMID 19424493, 2009). "The lymphopenia gene has a frame-shift mutation in the Gimap5 gene, resulting in absence of expression of the Gimap5 anti-apoptopic protein." (PMID 33815287, 2021). "Non-functional mutations of Gimap5 in both rats and mice are associated with severe peripheral T cell lymphopenia and increased susceptibility to autoimmune conditions such as type 1 diabetes and inflammatory bowel disease." (PMID 29718959, 2018). "We defined coevolutionary clusters that were unique to each disease strain and among these clusters of genes identified two genes, Add1 and Gimap5, previously shown by positional cloning to underlie susceptibility to hypertension in MHS and lymphopenia and diabetes in BBDP, respectively." (PMID 23890820, 2013). "Gimap5 −/− mice exhibit peripheral T-cell lymphopenia, especially of CD8+ T-cells." (PMID 21637352, 2010). "Among the seven Gimap genes, the Gimap5 frameshift mutation, a mutant allele that produces no protein, had the greatest impact on lymphopenia in the DR.lyp/lyp rat." (PMID 19421422, 2009). "Aside from Gimap5, only Gimap1 and Gimap3 could potentially play a role inthe development of lymphopenia, as they are the only remaining genes locatedwithin the 33 Mb interval critical for lymphopenia between D4Rhw6 andIIsnp3." (PMID 19421422, 2009). "In addition to T and B lymphopenia, both lines of mice show exhaustion of hematopoietic stem cells (HSC) and hepatic extramedullary hematopoiesis that is independent of T and B lymphocytes, as Rag1-/-Gimap5-/- mice also show the same phenotype." (PMID 34135906, 2021).
diabetes (12 papers, 2009 to 2025). "Our previous analysis of recombination events that reduced the contribution of DP, which was replaced by DR DNA, suggested that a “diabetes gene” would be located proximal to the Gimap5 mutation." (PMID 41042382, 2025). "In this rat, 1) spontaneous diabetes rarely occurs before 50 days of age; 2) 100% of the rats of both sexes develop diabetes before 80 days of age; and 3) a diabetes genetic susceptibility locus, Iddm14, was identified proximal to the Gimap5 mutation." (PMID 33815287, 2021). "Reconstitution of the lymphopenic BB-DP rats with splenocytes from syngenic, diabetes-resistant (BB-DR) rats that carry the wildtype Gimap5 allele eliminated the cycling of endogenous BB-DP T cells that were eventually lost from the periphery." (PMID 34135906, 2021). "Mutation in the founding member of this gene family, Gimap5, results in the lymphopenic phenotype in Bio-Breeding diabetes prone rats." (PMID 27023180, 2016). "We conclude that there are a limited number of genetic factors, including but not limited to Gimap4 and Gimap5, that are related to the increase in IgE levels, insulitis, infiltration of CD3+ and ED1+ cells, and beta cell loss prior to diabetes onset in congenic sBBM Gimap5-DP rats." (PMID 41042382, 2025). "In diabetes prone Bio Breeding rats, the lyp allele arises from a frame-shift mutation within the GTPase domain of the immune associated nucleotide binding protein 5 (Gimap5) gene." (PMID 27023180, 2016). "GIMAP5 gene mutations have been shown to contribute to T1D in the rat model for diabetes." (PMID 19654878, 2009). "The BioBreeding diabetes-prone (BBDP) rat has a mutation in the Gimap5 gene that leads to spontaneous apoptosis of peripheral T cells by an unknown mechanism." (PMID 19424493, 2009). "By cross-sectional sampling, IgE was further analyzed in sBBM Gimap5−/− (Gimap5-DP) rats killed between 20 and 50 days of age (n = 1–9 rats at each age) and at diabetes onset." (PMID 41042382, 2025). "In diabetes-resistant sBBM Gimap5-DR rats, CD3+ T cells were observed within the islet interior, where beta cells are centrally located in rats, while ED1+ macrophages remained largely peripheral." (PMID 41042382, 2025). "Serum IgE levels increased in Gimap5−/− (Gimap5-DP) rats compared to controls, beginning approximately 20 days before diabetes onset." (PMID 41042382, 2025). "In the BioBreeding diabetes-prone strain of rats (BB-DP), loss of functional GIMAP5 (GTPase of the immune associated nucleotide binding protein 5) results in profound peripheral T lymphopenia." (PMID 34135906, 2021). "Recently, a novel member of the GTPase family was described as rIAN5 in the BB rat, and its mutation, which was identified in the Gimap5 (Ian5) gene (RNO4), results in T cell lymphopenia causing diabetes in this model." (PMID 27595114, 2016). "Among the proteins of the GIMAP family, Gimap5 has been studied in detail, as the gene is responsible for the lymphopenic phenotype in the diabetes prone Bio Breeding rats." (PMID 27023180, 2016). "To examine the potential role of ER stress in T cell death of Gimap5−/− rats, we compared the expression of ER chaperone proteins in lymph node cells and thymocyte lysates from Gimap5−/− BBDP and Gimap5+/+ BioBreeding diabetes-resistant (BBDR) rats." (PMID 19424493, 2009). "For clarity, Gimap5-DR (DR for Diabetes Resistant) refers collectively to homozygous wildtype (BB DR.Gimap5+/+) and heterozygous (BB DR.Gimap5+/−) rats, both of which are diabetes-resistant." (PMID 41042382, 2025). "The unexpected finding that Gimap5, along with Gimap4, may regulate diabetes development in the BB rat is likely to translate into human type 1 diabetes autoimmunity." (PMID 41042382, 2025). "Furthermore, flow cytometry analyses on Gimap5−/− T cells from congenic WF.ART2a.Gimap5−/− rats that do not develop spontaneous diabetes but carry the Gimap5 null mutation have increased expression of ER stress response proteins, including GRP78 and CHOP." (PMID 19424493, 2009).
diabetes (continued). "Overall, this indicates that ER stress response signaling in T cells from the BBDP rat is a result of the absence of functional Gimap5 protein product and not a secondary consequence of spontaneous diabetes development." (PMID 19424493, 2009). "To ensure that ER stress response signaling in T cells from the BBDP rat is due to absence of functional Gimap5 protein and not a byproduct of diabetes development, we only used nondiabetic BBDP rats for studies." (PMID 19424493, 2009). "Similar findings were also observed in congenic WF.ART2a.Gimap5−/− rats that harbor the same recessive mutation in the Gimap5 gene as do BBDP rats, but do not develop spontaneous diabetes." (PMID 19424493, 2009).
autoimmune disease (8 papers, 2009 to 2025). A disorder resulting from loss of function or tissue destruction of an organ or multiple organs, arising from humoral or cellular immune responses of the individual to their own tissue constituents. "GIMAP5 is known to regulate lymphocyte function and survival, particularly in T-cells and it has previously been associated with autoimmune diseases such as type 1 diabetes, lupus, and inflammatory bowel disease." (PMID 40133288, 2025). "In humans, GIMAP5 has been associated with autoimmune diseases although its function is poorly defined." (PMID 25944983, 2015). "Studies have found that Gimap5 could influence the survival of T cells and that polymorphisms in human Gimap5 genes are related to autoimmune diseases." (PMID 34604035, 2021). "Such a dysregulation may be occurring in autoimmune diseases associated with pathogenic Th17 cells, such as Crohn’s disease, T1D, and multiple sclerosis, or in Gimap5-associated diseases such as SLE, T1D, and allergic asthma." (PMID 29382851, 2018). "Gimap5 (GTPase of the immunity-associated protein 5) has been linked to the regulation of T cell survival, and polymorphisms in the human GIMAP5 gene associate with autoimmune disorders." (PMID 19424493, 2009). "The critical role of Gimap5 in Treg survival/function is also evident in Type 1 diabetes in BioBreeding rats and may clarify why polyadenylation polymorphisms in GIMAP5, leading to rather subtle changes in gene expression, are associated with human autoimmune diseases such as T1D and SLE." (PMID 25944983, 2015). "Until now, it has been known that a loss of Gimap5 function causes T cell lymphopenia in rats due to the near complete loss of post-thymic peripheral CD8 T cells, which triggers a lethal autoimmune disease." (PMID 25038616, 2014). "GIMAP5 encodes a protein belonging to the GTP-binding superfamily and to the immune-associated nucleotide (IAN) subfamily of nucleotide-binding proteins, and has been implicated in autoimmune diseases, lymphocyte homeostasis and apoptosis." (PMID 24915441, 2014).
type 1 diabetes (8 papers, 2010 to 2025). "An important feature of the sBBM Gimap5-DP rats is their inability to produce any of the islet antigen autoantibodies that are strongly associated with human type 1 diabetes." (PMID 41042382, 2025). "A frameshift mutation in Gimap5 is a prerequisite for the development of spontaneous type 1 diabetes in rats." (PMID 25038616, 2014). "In humans, polyadenylation polymorphisms in GIMAP5 are associated with increased concentrations of IA2 autoantibodies in type 1 diabetes (T1D) patients and an increased risk of systemic lupus erythematosus SLE." (PMID 25944983, 2015). "Gene–gene interactions were noted between GIMAP4 and IL2RA, a known human type 1 diabetes risk gene, as well as between GIMAP5 and INS, a major type 1 diabetes risk gene strongly associated with insulin autoantibodies as the first appearing islet autoantibody." (PMID 41042382, 2025).
systemic lupus erythematosus (7 papers, 2009 to 2025). An autoimmune multi-organ disease typically associated with vasculopathy and autoantibody production. "A member of this family, GIMAP5, has an important role in human immune modulation as a polyadenylation polymorphism in the human GIMAP5 gene increases systemic lupus erythematosus risk and is also associated with elevated islet autoantibodies in type 1 diabetics." (PMID 19424493, 2009). "GIMAP5 may be involved in the pathogenesis of systemic lupus erythematosus." (PMID 41042382, 2025). "Similarly, in systemic lupus erythematosus (SLE), a SNP (rs6598) in the proximal canonical PAS of GTPase, IMAP family member 5 (GIMAP5) produces the rare AATAGA hexamer." (PMID 32560344, 2020).